SEC11C (SEC11 homolog C, signal peptidase complex subunit)
Description:
Catalytic component of the signal peptidase complex (SPC) which catalyzes the cleavage of N-terminal signal sequences from nascent proteins as they are translocated into the lumen of the endoplasmic reticulum. Specifically cleaves N-terminal signal peptides that contain a hydrophobic alpha-helix (h-region) shorter than 18-20 amino acids.
Synonyms: SEC11L3; SPC21; SPCS4C
Tractability: Antibody: UniProt predicts a signal peptide or a membrane-spanning region. PROTAC: ubiquitination databases record sites on it; its protein half-life has been measured.
Gene: Protein-coding gene on chromosome 18 (59,139,475 to 59,158,837, forward strand). Ensembl gene ENSG00000166562.
Subcellular location: Endoplasmic reticulum membrane
Subcellular location (Human Protein Atlas): Nuclear membrane; Golgi apparatus
Pathways (Reactome):
Metabolism of proteins: SRP-dependent cotranslational protein targeting to membrane; Synthesis, secretion, and deacylation of Ghrelin; Synthesis, secretion, and inactivation of Glucagon-like Peptide-1 (GLP-1); Synthesis, secretion, and inactivation of Glucose-dependent Insulinotropic Polypeptide (GIP)
Disease: Maturation of DENV proteins; Maturation of hRSV A proteins
Cell-Cell communication: Regulation of CDH1 posttranslational processing and trafficking to plasma membrane
Gene Ontology:
Molecular function: protein binding; serine-type endopeptidase activity; signal peptidase activity; peptidase activity
Biological process: protein maturation; protein processing
Cellular component: endoplasmic reticulum membrane; signal peptidase complex; membrane
Genetic constraint (gnomAD): Loss-of-function variants: 5 observed, 11.9 expected, observed/expected ratio (o/e) 0.42, 90% interval 0.22 to 0.88. The upper end of that interval is the gene's LOEUF score, 0.88, which puts it in group 3 of 6, group 1 being the genes least tolerant of losing a copy. Missense variants: 91 observed, 144.52 expected, observed/expected ratio (o/e) 0.63, 90% interval 0.53 to 0.75. Synonymous variants: 50 observed, 52.05 expected, observed/expected ratio (o/e) 0.96, 90% interval 0.76 to 1.22.
Homologues: Orthologues: chimpanzee SEC11C (99% identical), mouse Sec11c (98% identical), rat Sec11c (98% identical), guinea pig SEC11C (97% identical), macaque SEC11C (92% identical), rabbit SEC11C (89% identical), dog SEC11C (81% identical), tropical clawed frog sec11c (80% identical), pig SEC11C (73% identical), Drosophila melanogaster twr (70% identical), Caenorhabditis elegans sec-11 (66% identical). Paralogues in human: SEC11A (74% identical).
Diseases named in the same sentence as SEC11C in open-access papers:
SEC11C is named in the same sentence as 8 diseases in open-access papers, as found by Europe PMC text mining. Sharing a sentence is not in itself a finding about the gene and the disease. The quoted sentences say what the papers report.
Flavivirus Infections (1 paper, 2018). Infections with viruses of the genus FLAVIVIRUS, family FLAVIVIRIDAE. "SEC11C, a subunit of the signal peptidase complex (SPCS), also behaves in this way, in agreement with the prior finding that this complex is essential for flavivirus infection." (PMID 29451494, 2018).
head and neck squamous cell carcinoma (1 paper, 2022). A squamous cell carcinoma that arises from any of the following anatomic sites: lip and oral cavity, nasal cavity, paranasal sinuses, pharynx, larynx, and salivary glands. "In the current study, we aimed to investigate the expression of the five microsomal signal peptidase complex (SPC) subunit genes (SEC11A, SEC11C, SPCS1, SPCS2, and SPCS3) in head and neck squamous cell carcinoma (HNSC) and to explore their prognostic value." (PMID 35653344, 2022).
tumor (5 papers, 2007 to 2023). "Several of these EPINs have promoters of differentially expressed genes (such as DLL1, STOM and SEC11C in the GEPIA tumor/normal dataset; ID2, RPS27, SEC11C, CASZ1, CRTC2, C5 and STOM in the LNCaP/LHSAR dataset; see Methods, Differential Gene Expression)." (PMID 38057321, 2023). "Importantly, most of BRGs (25/28) in BRGPs signature, except CCR7, HERUD1 and SEC11C, were differently expressed among NSCLC tumor and normal tissue." (PMID 36389757, 2022). "We found two deleted regions shared by both tumor types in three out of the four cell lines H23R, A2780R, and OVCAR3R, but not in H460 cells, located on 18q21.2–18q21.31 and 18q21.32, affecting the genes RAB27B, CCDC68, TCF4, TXNL1, WDR7, and BOD1P; and genes ZNF532, SEC11C, GRP, respectively." (PMID 32224864, 2020).
infection (2 papers, 2012 to 2015). The state of being infected such as from the introduction of a foreign agent such as serum, vaccine, antigenic substance or organism. "In contrast, SEC11C blocked only the late stage of infection as only the expression of the late-protein, pp28 was reduced." (PMID 26599541, 2015). "Prior to the infection, B-lymphocytes were the major producers of PRDX4, SEC11C, ERLEC1 and TXNDC5 and all immunoglobulins." (PMID 23094107, 2012). "The expression of PRDX4, SEC11C, ERlEC1 and TXNDC5 decreased in expression in B-lymphocytes after S. Enteritidis infection suggesting a suppression of common B-lymphocyte function and specialization of B-lymphocyte towards immunoglobulin expression after the infection." (PMID 23094107, 2012).
SEC11C also shares sentences with these, for which no sentence is quoted: cancer (2 papers); COVID-19 (1); lung adenocarcinoma (1); parathyroid adenoma (1).